GBP4 (guanylate binding protein 4)
Description:
Interferon (IFN)-inducible GTPase that plays important roles in innate immunity against a diverse range of bacterial, viral and protozoan pathogens (By similarity). Negatively regulates the antiviral response by inhibiting activation of IRF7 transcription factor (By similarity).
Synonyms: Mpa2
Tractability: Antibody: its Gene Ontology location is reachable by antibodies, with high confidence. PROTAC: UniProt records ubiquitination sites on it; ubiquitination databases record sites on it; its protein half-life has been measured.
Gene: Protein-coding gene on chromosome 1 (89,181,144 to 89,198,942, reverse strand). Ensembl gene ENSG00000162654.
Subcellular location: Golgi apparatus membrane; Cytoplasm; Nucleus; Cytoplasm, perinuclear region
Subcellular location (Human Protein Atlas): Golgi apparatus; Plasma membrane
Pathways (Reactome):
Immune System: CASP4 inflammasome assembly; GBP-mediated host defense; Interferon gamma signaling
Disease: Enterobacterial factors antagonize host defense
Gene Ontology:
Molecular function: identical protein binding; protein binding; protein homodimerization activity; GTP binding; GTPase activity
Biological process: cellular response to type II interferon; defense response to Gram-positive bacterium; defense response to protozoan
Cellular component: cytosol; Golgi apparatus; Golgi membrane; nucleus; perinuclear region of cytoplasm; cytoplasmic vesicle; cytoplasm
Genetic constraint (gnomAD): Loss-of-function variants: 66 observed, 59.47 expected, observed/expected ratio (o/e) 1.11, 90% interval 0.91 to 1.36. The upper end of that interval is the gene's LOEUF score, 1.36, which puts it in group 5 of 6, group 1 being the genes least tolerant of losing a copy. Missense variants: 625 observed, 708.17 expected, observed/expected ratio (o/e) 0.88, 90% interval 0.83 to 0.94. Synonymous variants: 257 observed, 260.07 expected, observed/expected ratio (o/e) 0.99, 90% interval 0.89 to 1.1.
Homologues: Orthologues: chimpanzee GBP4 (99% identical), rat Gbp4 (69% identical), mouse Gbp3 (68% identical), mouse Gbp7 (68% identical), rat Gbp7 (68% identical), rat Gbp6-ps2 (59% identical), Drosophila melanogaster atl (18% identical). Paralogues in human: GBP7 (76% identical), GBP6 (69% identical), GBP1 (51% identical), GBP2 (50% identical), GBP3 (50% identical), GBP5 (47% identical), ATL2 (19% identical), ATL3 (19% identical), ATL1 (19% identical), RNF112 (12% identical).
Diseases named in the same sentence as GBP4 in open-access papers:
GBP4 is named in the same sentence as 46 diseases in open-access papers, as found by Europe PMC text mining. Sharing a sentence is not in itself a finding about the gene and the disease. The quoted sentences say what the papers report.
melanoma (10 papers, 2018 to 2025). A malignant, usually aggressive tumor composed of atypical, neoplastic melanocytes. "The GTP-binding protein 4 (GBP4) was previously identified as a prognostic signature gene that separates melanoma patients into low- and high-risk groups according to survival." (PMID 36135194, 2022). "GBP4 enhances melanoma immune checkpoint responses, reflecting TME dynamics and aiding anti-EGFR therapy in non-small cell lung cancer, linked to its Golgi and plasma membrane localization." (PMID 40564939, 2025). "The expression level of guanylate-binding protein 4 gene (GBP4) has been shown in a previous study increased in melanoma tissue, which is consistent with our experiment." (PMID 40652057, 2025). "GBP4 is a guanosine monophosphate binding protein, and many studies have shown that GBP4 is a good prognostic marker for melanoma." (PMID 37207210, 2023). "A high expression of GBP4 was correlated with favorable overall survival in skin (cutaneous) melanoma patients followed for over 30 years." (PMID 34054929, 2021). "In addition, a recent study found the GBP4 was positively correlated with immune cell infiltration in melanoma patients." (PMID 34769455, 2021). "Furthermore, GBP1 reduces radioresistance of two human oral and liver cancer cell lines and correlates with better prognosis in melanoma but with poorer prognosis in human glioblastoma, (iii) GBP4 inhibits innate responses to viral infection but lacks known tumor related functions to date." (PMID 32265897, 2020). "We also found that the overexpression of GBP4, DOK1, DDX60, and IFIH1 is correlated with better overall survival in several melanoma datasets." (PMID 34769455, 2021). "The qRT-PCR results showed that the expression levels of four genes, FCGR2, GBP4, SLC5A3 and GJA1, in melanoma cells were different from that in normal melanocyte, which was consistent with the statistical results of the samples we obtained in the public database." (PMID 40652057, 2025). "Treg signature genes CXCR5, TNFRSF9, CCR7, STAT1, GBP4, and EOMES were significantly upregulated in the young cohort and were correlated with higher survival in melanoma, while ID3, IL-17A, IL-17F, RDH10 and IL-11 were significantly upregulated in the old cohort." (PMID 36135194, 2022). "The overall survival rate of patients with high expressions of CCR7, CXCR5, EOMES, GBP4, TNFRSF9 and STAT1 in melanoma was significantly higher, which is consistent with the significantly higher survival rate observed for the young cohort receiving immunotherapy." (PMID 36135194, 2022). "By analyzing the TCGA genomics, we also found that the gene alteration rates in the melanoma TCGA dataset were 12% for DDX60, 5% for CSNK1E, 2.8% for FGD1, 2.1% for GBP4, 4% for IFIH1, 1% for DOK1, and 0.7% for IRX3, and these alterations were not significantly correlated with mRNA expression." (PMID 34769455, 2021). "When comparing the FFPE with the FF melanoma signature, two candidate genes were missing (esophageal cancer–related gene 2 [ECRG2] and hairy and enhancer of split 6 [Drosophila] [HES6]) and guanylate binding protein–4 (GBP4) was included." (PMID 31360859, 2018). "While three of the signature genes (KLHL41, KRT9, GBP4) have not been reported so far to be expressed in melanoma, there is functional evidence for all signature genes suggesting that they might be involved in immune responses, inflammation, or tumor progression." (PMID 31360859, 2018).
viral infection (10 papers, 2011 to 2025). "Notably, Gbp4−/− deficient mice alone showed increased serum IFN-α, consistent with Gbp4’s reported role in negatively regulating IFN-α via IRF7 during viral infection." (PMID 40607809, 2025). "Therefore, GBP4 may affect ubiquitination-mediated pathways, thereby inhibiting viral infection." (PMID 32269280, 2020).
breast carcinoma (5 papers, 2017 to 2025). "In another study, correlation between GBP4 and 5‐year survival rate was favorable in colorectal cancer and breast cancer." (PMID 33350104, 2021). "Notably, our findings indicate that the genes upregulated by O-desmethyltramadol in both breast cancer cell lines—IFIT1, GBP4, SECTM1, and OASL—are regulated by interferon." (PMID 40362379, 2025). "Our findings that IRF1 expression contributes to the regulation of RARRES3, GBP4, and CTSS, but not to the regulation of TNFSF10, are further validated by mRNA expression data from breast cancer patients." (PMID 29192143, 2017).
skin cutaneous melanoma (4 papers, 2020 to 2022). "The expression of GBP4 could improve the sensitivity and specificity for predicting skin cutaneous melanoma." (PMID 33350104, 2021).
COVID-19 (3 papers, 2022 to 2024). A disease caused by infection with severe acute respiratory syndrome coronavirus 2. "IFN-related genes, such as ISG15, IFITM1 and GBP4, were also downregulated in B_naive and B_activated of severe compared to moderate COVID-19." (PMID 37095364, 2023). "Further, they observed that key driver genes, which were upregulated with COVID-19 and IBD inflammation (e.g., CXCL1, GBP4, SOCS3, PARP14, and PARP9), were downregulated following the use of infliximab." (PMID 36060521, 2022).
gastric cancer (3 papers, 2017 to 2025). A primary or metastatic malignant neoplasm involving the stomach. "The data revealed a gene expression pattern in EBV-positive gastric cancer, highlighting immune response, inflammation, and cell proliferation genes (e.g., GBP4, ICAM1, IL32, TNFSF10)." (PMID 40110195, 2025).
colorectal cancer (2 papers, 2021). A primary or metastatic malignant neoplasm that affects the colon or rectum. "Recently, it was shown that GBP1 and GBP4 are IFNG-dependent and were directly co-expressed with CD8A in colorectal cancer." (PMID 34487971, 2021).
leukemia (2 papers, 2021 to 2024). A malignant (clonal) hematologic disorder, involving hematopoietic stem cells and characterized by the presence of primitive or atypical myeloid or lymphoid cells in the bone marrow and the blood. "In this study, we revealed that GBP1–5 are significantly downregulated in AML, ALL, or CLL patients compared with the non-leukemic population, and elevated levels of GBP1, GBP3, GBP4, and GBP6 are associated with prolonged survival time in leukemia and lymphoma patients." (PMID 34294680, 2021). "GBP1, GBP3, GBP4, and GBP6 were beneficial for overall survival, indicating that GBPs are favorable prognosis markers for tested leukemia and lymphoma types." (PMID 34294680, 2021).
parasitemia (2 papers, 2021 to 2025). "Notably, mice deficient in both Gbp4 and Irgb6 showed significantly enhanced survival despite unaltered peripheral parasitemia and BBB integrity." (PMID 40607809, 2025). "We infected Gbp4−/−, Irgb6−/−, and WT control mice with PbA parasites and observed parasitemia and host survival." (PMID 40607809, 2025). "Functional studies demonstrated that Gbp4 deficiency alone did not alter parasitemia or survival, whereas Irgb6-deficient mice displayed reduced parasitemia and improved survival outcomes." (PMID 40607809, 2025). "Notably, the prolonged survival observed in Irgb6−/− Gbp4−/− mice, despite unchanged parasitemia, suggests that these genes may act in concert to modulate immune responses during ECM." (PMID 40607809, 2025). "Significantly prolonged survival and reduced parasitemia were observed in the Irgb6−/− mice compared to WT counterparts, but not in the Gbp4−/− mice." (PMID 40607809, 2025).
Salmonella Infections (2 papers, 2010 to 2024). Infections with bacteria of the genus SALMONELLA. "It is tempting to speculate that the loss of GBP2 led to the expansion of GBP4 in M. Myotis and E. fuscus since, in humans, upon Salmonella infection, GBP1 requires GBP2 and GBP4 to recruit caspase-4 to the surface of the bacteria." (PMID 38357541, 2024). "IFNG, GBP4, and GBP5 showed dramatic increase post Salmonella infection." (PMID 21172007, 2010).
asthma (1 paper, 2022). "To date, no studies have reported on the relationship between CD3D, CD3G, RGS1, HLA-DMB, GBP4, GBP5, and asthma." (PMID 36118895, 2022).
breast tumors (1 paper, 2013). "A subset of the genes, such as Stat1 and Gbp4, were also up-regulated in adenoma tumors, suggesting that elements of the pathway were active in early breast tumors." (PMID 23520493, 2013).
celiac disease (1 paper, 2022). An autoimmune genetic disorder with an unknown pattern of inheritance that primarily affects the digestive tract. "The most significantly up-regulated genes in celiac disease were TAP1, HLA-E, HCP5, STAT1, GBP1, STAT1, LOC100419583, and GBP4 and the down-regulated ones were IDS, PKIB, FBXO2, OXT, and ADI1." (PMID 36011206, 2022).
cerebral malaria (1 paper, 2025). A sequestration of Plasmodium falciparum in the brain, which can cause coma and/or seizures. "Through RNA sequencing of the olfactory bulb (OB) in a murine experimental cerebral malaria (ECM) model, we identified the early upregulation of interferon (IFN)-inducible GTPases, Irgb6 and Gbp4, key effectors downstream of IFN-γ signaling." (PMID 40607809, 2025).
colorectal adenocarcinoma (1 paper, 2021). The most common type of colorectal carcinoma. "The differential expression analysis of 5561 proteins in 95 colorectal adenocarcinoma (COAD) samples indicated high levels of TAP2 (log Fold Change [FC] = -1.33), PARP14 (logFC = -1.25), and GBP4 (logFC = -1.09) in the RSI-Low tumours." (PMID 34078917, 2021).
leishmaniasis (1 paper, 2025). Infectious disease that is transmitted through the bite of hematophagous female phlebotomine sand flies. "Increased expression of Gbp4 has been associated with several diseases, including cancer, leishmaniasis, chikungunya, and malaria (41, –, 44)." (PMID 40607809, 2025).
lung injury (1 paper, 2026). "YTHDF1 can facilitate the translation of guanylate binding protein 4 (GBP4), promoting M1 polarization in acute lung injury, while m6A-regulated circRNA-miRNA axes, such as circ_0066715/miR-486-5p/ETS proto-oncogene 1 (ETS1) axis, are closely associated with M2 polarization in rheumatoid arthritis." (PMID 41376856, 2026).
lymph node metastasis (1 paper, 2023). "We also found that the expression of the three LINC01871‐related mRNAs, namely, IDO1, CXCL10, and GBP4, was highly negatively correlated with TNM stage, lymph node metastasis, and liver metastasis." (PMID 38083905, 2023).
neuroblastoma (1 paper, 2022). Neuroblastoma (NB) is the most common solid, extracranial childhood tumor. "We further validated our results in JEV infected human neuroblastoma SH-SY5Y cells, where we observed significantly enhanced transcript levels of Gbp1, Gbp2, Gbp4 & Gbp5." (PMID 35663470, 2022).
oral cancers (1 paper, 2025). "GBP4 in oral cancers, when unmethylated, may drive sarcoma progression, hinting at cytoskeletal roles via integrin or actin dynamics, though mechanisms require further elucidation." (PMID 40564939, 2025).
oropharyngeal cancer (1 paper, 2023). Carcinoma, predominantly squamous cell, arising from the epithelial cells of the oropharynx. "Most of the oral and oropharyngeal cancer samples were unmethylated in almost all the investigated gene promoters: EDARADD, GBP4, HAVCR2, HLA DPB1, IL12RB1, MARCO, and SIGLEC12." (PMID 37175405, 2023).
pancreatic cancer (1 paper, 2024). "The scatterplots showed that, as the expression of COL17A1/GBP4/CDC6 increased and the risk score increased, the survival time of each pancreatic cancer patient decreased and the proportion of death increased." (PMID 39376555, 2024). "This suggests that GBP4 is not closely related to the invasiveness and metastasis of pancreatic cancer." (PMID 39376555, 2024).
tularemia (1 paper, 2019). Tularemia is an infection caused by the bacterium Francisella tularensis. "Tularemia vaccine induced higher guanylate binding protein (GBP) responses at Day 2, with upregulation of genes encoding for GBP1P1, GBP5, GBP1, and GBP4 compared to the other vaccines at Day 3 (blue bracket)." (PMID 31878161, 2019).
tumor (21 papers, 2017 to 2026). "Previous studies showed that GBP4 was associated with tumorigenesis and progression via modulate tumor immune microenvironment." (PMID 39376555, 2024). "Logically, patients expressing high levels of GBP4 should, in theory, exhibit a more favorable response to immunotherapy owing to’the association of GBP4 with an inflamed tumor microenvironment (TME)." (PMID 38347243, 2024). "In summary, GBP4 is strongly associated with an inflamed tumor microenvironment (TME), underscoring its potential diagnostic utility in assessing the immunogenicity of NSCLC." (PMID 38347243, 2024). "Furthermore, GBP4 demonstrated positive associations with immunomodulatory factors, tumor-infiltrating immune cells (TIICs) and inhibitory immune checkpoints." (PMID 38347243, 2024). "Several ISGs such as GBP family genes Gbp4 and Gbp5, Cxcl9, Oas2, and Stat1, were significantly downregulated in the old Tumor-3 subcluster." (PMID 41332581, 2025). "Emerging evidence suggests that GBP4 serves as a robust pan-cancer biomarker for evaluating tumor immunological characteristics and predicting therapeutic responses." (PMID 40362379, 2025). "Subsequently, we explored the correlations between GBP4 and immunological features within the tumor microenvironment (TME) in non-small cell lung cancer (NSCLC) patients." (PMID 38347243, 2024). "GBP4 expression was more highly upregulated in tumor tissues than in paracancerous tissues at the protein level." (PMID 38347243, 2024). "Taken together, these data suggest that GBP4 is a pan-cancer marker for high immunogenicity, except in a few tumor types." (PMID 38347243, 2024). "Next, a pan-cancer analysis of the immunological features of GBP4 was conducted for all accessible tumor types in the TCGA database." (PMID 38347243, 2024). "GBP4 is a guanylate-binding protein that is involved in pathological processes such as tumor formation and progression." (PMID 36268281, 2022). "Consistent with RNAseq data, GBP2 expression was higher in normal tissues (p = 1.877130e-04), and GBP4 expression was higher in tumor tissues (p = 1.25852508986603e-08)." (PMID 36246628, 2022). "This study identified tumor microenvironment-related genes, including monokine induced by gamma interferon (MIG or CXCL9), E26 transformation-specific variant 7 (ETV7), guanylate binding protein 4 (GBP4), and CD3 epsilon chain (CD3E)." (PMID 34054929, 2021). "GBP4 exhibits a split personality—favoring survival in ovarian cancer by supporting immune responses through immunomodulatory factors, yet worsening renal cancer outcomes by enhancing tumor resilience, echoing GBP1’s duality." (PMID 40564939, 2025). "Overall, GBP4 might be a promising biomarker for identifying tumor immunogenicity and guiding immunotherapy." (PMID 38347243, 2024). "The data again emphasize key differences between cell lines and primary tumors and that future functional studies, such as RNA silencing or over-expression of IFI30, GPB1, and GBP4 should be performed in primary tumors to evaluate the function of such factors in the tumor microenvironment context." (PMID 32265897, 2020). "Significant differences were observed between tumor and normal samples for MRI1| chr19:13883962, GBP4| chr1:89649327, and FCF1| chr14:75203040." (PMID 39091293, 2024). "The high-GBP4 group exhibited higher ESTIMATE scores, immune scores, and stromal scores but lower tumor purity than the low-GBP4 group." (PMID 38347243, 2024). "DOK2, GBP4, PSMB9, and NLRC5 were significantly changed according to methylation subgroups, survival, tumor stages, and T categories and were positively correlated, which was validated in the testing group (P < 0.05)." (PMID 36268281, 2022). "Immunohistochemistry of primary tumor tissue was performed for eight proteins: COL6A6, DCD, GBP4, KLHL41, KRT9, PIP, SCGB1D2, SCGB2A2." (PMID 34757537, 2022). "On the contrary, the expressions of GBP3, GBP4, and GBP5 in tumor tissues were significantly higher than those in normal tissues." (PMID 36246628, 2022).
tumor (continued). "Guanylate-binding protein 4(GBP4) belongs to the interferon-stimulated factor that acts as a protective factor in host defense, and several genes from the GBP family act as tumor suppressors." (PMID 34769455, 2021). "GBP4 overexpression promotes the infiltration of exhausted CD8+ T cells and tumor progression." (PMID 40564939, 2025). "IFI30, GBP1 and GBP4 were upregulated 2-8-fold (p < 0.0001) in IFNγ positive tumors vs. IFNγ negative tumors in each of the six tumor types." (PMID 32265897, 2020). "In addition, high levels of HCST, C3AR1, GBP4, LY96, ANKRD22, FPR3 and FCGR2A, have also been related to immune activation and/or inflammatory response in tumours; however, their role in basal-like breast malignancies are yet to be uncovered." (PMID 28351365, 2017). "Results suggest that AKAP12, APOL3, CXCL13, CXCL9, GBP4, and LRIG1 may act as tumor suppressors." (PMID 35677536, 2022). "However, the relationship between GBP4 and tumor immunity has not been explored." (PMID 38347243, 2024).